ENSG00000252993
Gene: Small nucleolar RNA gene on chromosome 10 (92,076,242 to 92,076,365, forward strand). Ensembl gene ENSG00000252993.
Homologues: Orthologues: mouse Gm56345 (60% identical), mouse Gm54634 (41% identical). Paralogues in human: SNORA25B (74% identical), SNORA25 (68% identical).